INS (insulin)
Diseases named in the same sentence as INS in open-access papers (continued):
Sharing a sentence is not in itself a finding about the gene and the disease.
type 2 diabetes (continued). "In conclusion, this study contributes to the existing body of evidence supporting the efficacy of GLP-1 RAs added to insulin therapy in patients with uncontrolled type 2 diabetes." (PMID 37589043, 2023). "Therapies for people with type 2 diabetes include various classes of drugs, such as insulin sensitizers, insulin secretagogues, incretin analogs, biguanides, α-glucosidase inhibitors, dipeptidyl peptidase-4 inhibitors, and intestinal lipase inhibitors." (PMID 38203600, 2023). "In type 2 diabetic rat animal models, Gastrodia significantly improved hypothalamic insulin signaling, enhanced insulin sensitivity, and reduced hepatic glycogen output in a hyper insulinemic state." (PMID 37114145, 2023). "The increased level of TNF‐α induces insulin resistance in adipocytes and peripheral tissues by impairing the insulin signaling, which leads to the development of type 2 diabetes." (PMID 36655073, 2023). "Those mRNAs were mainly involved in insulin signaling pathway, type II diabetes mellitus, Fc epsilon RI signaling pathway, inositol phosphate metabolism, and GnRH secretion." (PMID 37550765, 2023). "Insulin treatment simplification with IDegLira in selected patients with type 2 diabetes is safe, maintains adequate glycaemic control and is associated with weight loss over 12 months." (PMID 36461758, 2023). "Most (64/92, 70%) participants had type 2 diabetes and had used insulin for an average of 12 (SD 12) years." (PMID 36826987, 2023). "We aimed to evaluated the effect of premixed insulin (Ins), premixed insulin combined with metformin (Ins+Met) or mulberry twig alkaloids(Ins+SZ-A) on blood glucose fluctuations in patients with type 2 diabetes (T2DM) using continuous glucose monitors (CGM)." (PMID 38027146, 2023). "Advanced glycation end-products are produced by type 2 diabetes and impaired insulin sensitivity, which leads to the generation of inflammatory cytokines and predisposes individuals to inflammatory conditions like periodontitis." (PMID 37394484, 2023). "For instance, chronic NaHS treatment can promote glucose uptake in both myotubes and adipocytes by increasing insulin sensitivity and ameliorates kidney lesions in type 2 diabetes in diabetic rats." (PMID 36769221, 2023). "Using CGM and the recommended CGM targets, we wanted to evaluate low-premix insulin analogue therapy (biphasic aspart/NovoMix 30 and biphasic lispro 25/Humalog Mix 25) in real-world type 2 diabetes patients for glycaemic efficacy and especially hypoglycaemia." (PMID 36882852, 2023). "Compared with healthy individuals, incretin-induced insulin secretory responses in type 2 diabetes seem to be reduced more, with less well-controlled plasma glucose concentrations (indicated by lower baseline HbA1c levels, fewer diabetes medications)." (PMID 37430117, 2023). "Type 2 diabetes is a metabolic disease that affects insulin activity in regulating blood glucose levels." (PMID 37332343, 2023). "ICU patients with type 2 diabetes experience acute-on-chronic insulin resistance, and typically require high insulin doses to achieve target blood glucose levels." (PMID 37194077, 2023). "It is widely believed that acupuncture can reduce obesity and type 2 diabetes by increasing insulin sensitivity." (PMID 38155665, 2023). "In type 2 diabetes, the increase in blood glucose initially results from insulin-resistance, or the inability of the body cells to respond fully to insulin." (PMID 37728724, 2023). "All participants in our study were likely to have had lower AMPK activity because they were insulin-resistant (i.e., they had type 2 diabetes)." (PMID 36854023, 2023). "Many studies have demonstrated that IR is the earliest abnormality in the natural history of type 2 diabetes, due to defects in both the action of insulin (IR) and its secretion (beta cell dysfunction)." (PMID 37298967, 2023).
type 2 diabetes (continued). "Milk-derived whey as well as casein proteins can produce insulin secretion in obese, pre-diabetic, and also type 2 diabetes individuals." (PMID 36904293, 2023). "A key clinical feature for the recognition of adults who are initially diagnosed as type 2 diabetes who have misdiagnosed type 1 diabetes is that insulin is rapidly required to control hyperglycaemia." (PMID 37728732, 2023). "Camel milk can be used in the treatment of type 1 and type 2 diabetes due to the high level of insulin—approximately 52–59 units/liter and insulin-like substances." (PMID 38139380, 2023). "We evaluated the effect of type 2 diabetes by simulating the response to insulin, but now in a type 2 diabetic condition." (PMID 37286693, 2023). "Basal insulin glargine has a neutral effect on cardiovascular risk in type 2 diabetes (T2DM)." (PMID 36894921, 2023). "Here, we demonstrate lower β‐catenin protein abundance in insulin resistant mice, and perturbed β‐catenin phosphorylation in men with type 2 diabetes." (PMID 36807886, 2023). "The mother was a 29-year-old Caucasian primigravida female with past medical history of poorly controlled type 2 diabetes managed with metformin prior to pregnancy, prompting admission for glucose management and initiation of insulin at 13 weeks." (PMID 38001547, 2023). "Insulin is the mainstay of treatment for type 1 diabetes and is also used in patients with type 2 diabetes who have failed on non-insulin AHAs." (PMID 36789141, 2023). "Pancreatic ADC values of newly diagnosed type II diabetes patients treated with insulin + metformin can be used as a marker of pancreatic function in the evaluation of response to treatment and clinical decisions." (PMID 38234946, 2023). "Insulin therapy is the preferred pharmacological approach to manage hyperglycemia in hospitalized patients with type 2 diabetes." (PMID 36964858, 2023). "Negative associations were found for metabolic (including glycemic), lipid, and anthropometric traits including fat mass, fat-free mass, BMI, obesity, type 2 diabetes, fasting insulin, insulin resistance, and leptin." (PMID 36650572, 2023). "The pharmacological interventions in type 2 diabetes are mainly based on drugs that stimulate insulin secretion or sensitivity to insulin." (PMID 38137892, 2023). "Patients ≥14 years old with type 1 or type 2 diabetes treated with insulin for more than a year were included." (PMID 37964960, 2023). "In this study, we developed a voice-based conversational artificial intelligence (VBAI) application to help patients with type 2 diabetes manage basal insulin titration at home." (PMID 38039007, 2023). "Insulin therapy is the standard therapy for patients with type 1 diabetes, and it is the recommended course of treatment for some patients with type 2 diabetes." (PMID 37836872, 2023). "β-cell dysfunction is a prominent feature of type 2 diabetes that results in defects in glucose-stimulated insulin secretion." (PMID 36596838, 2023). "This combination is an option for type 2 diabetes patients who are unable to achieve their glycemic goals (HbA1c > 7.5%) with basal insulin alone." (PMID 37598203, 2023). "By regulating glucose and lipid metabolism and enhancing insulin sensitivity, broccoli can reduce the risks of metabolic syndrome, type 2 diabetes, and cardiovascular diseases." (PMID 38260084, 2023). "This implies that, as is the case with type II diabetes, these piglets had compromised insulin sensitivity; the pigs had to produce significantly more insulin to trigger the metabolic processes required to process the incoming glucose." (PMID 36984860, 2023). "In particular, the results of the KEGG analysis showed that CACNA1C was enriched in multiple pathways including type 2 diabetes and insulin secretion." (PMID 36901708, 2023).
type 2 diabetes (continued). "In patients with type 2 diabetes, the incretin effect is greatly impaired, which induces insufficient insulin secretion and insufficient suppression of glucagon secretion, resulting in postprandial hyperglycemia." (PMID 37762244, 2023). "Our study adds to the existing literature by reinforcing that the use of CGM devices can lead to improved glycemic control in hospitalized patients with type 2 diabetes on intensive insulin therapy." (PMID 37736430, 2023). "Type 2 diabetes (T2D) is characterized by insulin insensitivity in target tissues resulting in hyperglycemia." (PMID 36711657, 2023). "It is commonly accepted that during the natural course from normoglycemia to frank type 2 diabetes, insulin secretion follows the pattern of an inverted U, also termed ”Starling’s curve of the pancreas”." (PMID 36901984, 2023). "For two of the beta cell expression modules, we find enrichment in genes related to type 2 diabetes, one of which shows strong enrichment in pathways related to insulin secretion." (PMID 37333221, 2023). "Overall, this adipogenic role, coupled with the finding that such brown-like adipose tissue improves beta-cell function through the attenuation of insulin demands, has made BMPs attractive targets for the treatment of type 2 diabetes." (PMID 37965235, 2023). "The insulin-promoting effect of GLP-1 in type 2 diabetes patients shows that it has a potential role in drug treatment of the disease." (PMID 36755915, 2023). "This explanation is consistent with a previous report showing a sustained increase in hematocrit in patients with type 2 diabetes treated with dapagliflozin who were also receiving chronic treatment with insulin." (PMID 37954838, 2023). "Human data was identified in the form of a case report on SGLT2 inhibitor use during pregnancy of a 31-year-old woman with type 2 diabetes on empagliflozin, metformin and insulin degludec who was found to be pregnant at the 5th week of gestation." (PMID 37881498, 2023). "We conducted a systematic review and meta-analysis to investigate the efficacy and safety of once-weekly insulin versus once-daily insulin in type 2 diabetes (T2D)." (PMID 38206709, 2023). "Insulin and metformin can be used in combination to treat early diagnosed type II diabetes patients." (PMID 38234946, 2023). "CpGs within the same gene region have previously been associated with type 2 diabetes-related traits in observational studies (BMI, waist circumference, HDL-cholesterol, insulin) and in Mendelian randomisation analyses (LDL-cholesterol)." (PMID 37202507, 2023). "Women who develop GDM present a metabolic condition similar to that found in type 2 diabetes, characterized by impaired insulin response." (PMID 37869250, 2023). "On the other hand, age (p=0.033) and customer purchasing insulin per month (p=0.038) were the only factors that are significantly related to community pharmacists' perceived role in type 2 diabetes." (PMID 37182028, 2023). "Physicians lack guidance as to which patients with insulin-requiring type 2 diabetes will respond best to GLP-1 RAs with respect to glycemic control, insulin dose reduction, and weight loss." (PMID 37589043, 2023). "In fact, defective insulin maturation with increased ER localization of proinsulin was reported in the beta cells of type 2 diabetes patients." (PMID 37152949, 2023). "Type 2 diabetes (T2D) is characterised by hyperglycaemia with elevated fasting and postprandial glucose, largely due to insulin resistance and lower beta cell function." (PMID 37176677, 2023). "MiRNAs are involved in regulating multiple biological processes in type II diabetes including insulin secretion, immune inflammatory response, angiogenesis and diabetic wound healing." (PMID 37860579, 2023). "Conversely, persistent high C-peptide levels (approximately >600 pmol/l) indicate substantial retained insulin secretion consistent with the treatment requirements and response of type 2 diabetes." (PMID 37728732, 2023).
type 2 diabetes (continued). "GLP-1RAs enhance glucose-dependent insulin release, reduce gastric emptying, and decrease glucagon secretion, making them effective drugs in type 2 diabetes management." (PMID 37239935, 2023). "Glucotoxicity and lipotoxicity in type 2 diabetes stress β cells by increasing insulin biosynthesis." (PMID 38071217, 2023). "Glucose intolerance in obese type 2 diabetics (T2D) is determined by defects in insulin secretion and action." (PMID 38020201, 2023). "This study presented the first plasma extrachromosomal circular DNA (eccDNA) landscape of type 2 diabetes mellitus treated with short‐term intensive insulin therapy." (PMID 37859516, 2023). "In this systematic review, the degree of impact on vitamin D supplementation on patients’ incidence of Type 2 Diabetes, as well as on their Insulin sensitivity, varied from study to study." (PMID 37123701, 2023). "Type-2 diabetes is a well-studied energy metabolism rewiring state in human pancreatic β-cells where glucose metabolism is uncoupled from insulin secretion." (PMID 37935795, 2023). "Activation of PPARγ has been shown toenhance insulin sensitivity, promote glucose uptake in adipose tissue and skeletal muscle, and reduce inflammation, which are criticalfactors in the pathogenesis of type 2 diabetes and metabolic syndrome." (PMID 37901293, 2023). "With type 2 diabetes (T2D), glucose levels start to rise when beta-cells are unable to meet the demands of insulin resistance." (PMID 37409234, 2023). "Plasma C16:1 t9 has been associated with higher LDL-C, but also with an improved metabolic profile, lower triglycerides, fasting insulin, blood pressure, and incident type II diabetes." (PMID 35931833, 2023). "In the context of the prevention and treatment of type 2 diabetes, polyphenols offer beneficial effects on the gastrointestinal tract, pancreatic endocrine functions, liver, and insulin-sensitive tissues." (PMID 37835351, 2023). "Hypoglycemia is common in patients with type 1 and type 2 diabetes (T1D, T2D), treated with insulin or sulfonylureas, and has multiple short- and long-term clinical implications." (PMID 37298308, 2023). "In most patients with type 2 diabetes, chronic insulin treatment and use of sulphonylureas induce weight gain, while metformin treatment has been consistently associated with modest weight loss." (PMID 37120538, 2023). "For example, STK25 is important in lipid metabolism associated with liver, muscle, and adipose tissues, and MST3 is associated with glucose metabolism in the liver or glucose and insulin homeostasis in a Type 2 diabetes mouse model." (PMID 36653023, 2023). "Treatment for type 2 diabetes typically involves the administration of oral medications such as insulin, various sulfonylureas, and metformin." (PMID 38068845, 2023). "VEGFA has been identified as a biomarker for a number of metabolic diseases due to its involvement in insulin secretion and the regulation of metabolic responses in type 2 diabetes (T2DM)." (PMID 37894852, 2023). "Type II diabetes is a chronic disease, which affects millions of people worldwide: the inadequate secretion of insulin by β-cells and/or insulin resistance in tissues are its main characteristics." (PMID 37284652, 2023). "Namely, we used a predefined protocol with new-initiators design, defined specific outcomes, used an insulin comparator that is also indicated in advanced stages of type 2 diabetes, and applied PS matching to balance the cohorts." (PMID 37244998, 2023). "It is an endocrine disorder characterized by hyperglycemia, resulting from impaired insulin secretion (type 1 diabetes) or altered insulin sensitivity (type 2 diabetes)." (PMID 37238844, 2023). "Salicylate, an IKKβ inhibitor, is under clinical trials for the treatment of type 2 diabetes, and its insulin-sensitizing effect is likely due to this inhibitor's broad spectrum of activity." (PMID 37346355, 2023).
type 2 diabetes (continued). "Type 2 diabetes, one of the major endocrine disorders, is characterized by impaired insulin secretion and/or impaired action of insulin at the cellular level." (PMID 37446567, 2023). "Healthy skeletal muscle can prevent and improve type 2 diabetes by increasing glucose intake and insulin sensitivity." (PMID 37170065, 2023). "Obese adults have a higher prevalence of metabolic problems, such as insulin irregularities, hyperglycemia, and Type-2 Diabetes." (PMID 38179409, 2023). "The insulin signaling pathway, type II diabetes mellitus and adipokine signaling pathways were all enriched." (PMID 37710320, 2023). "For instance, in a Spanish study, insulin dugladec was found to be the dominant strategy for treating type 2 diabetes patients when compared to insulin glargine." (PMID 36601214, 2023). "Previous research has drawn connections between low insulin usage and depression, embarrassment, a busy schedule, and travel among people living with type 2 diabetes." (PMID 36673730, 2023). "Compared to findings for a control group, continuous positive airway pressure (CPAP) therapy for six months improved glycemic control and insulin resistance in patients with poorly managed type 2 diabetes and OSA." (PMID 38050514, 2023). "Its effects on pancreatic β-cells, and therefore glucose homeostasis, have made it an important treatment option for type 2 diabetes in humans, as it improves glucose tolerance and insulin sensitivity." (PMID 37143501, 2023). "A 60-minute test meal C-peptide level was found to successfully predict switching from insulin therapy to liraglutide monotherapy among 69 patients with type 2 diabetes who were on a low 1.9-unit average daily insulin dose." (PMID 37589043, 2023). "The biochemical characteristics of the patients and the control group included lipid profiles, hormone profiles and indicators for type-2 diabetes, including free fasting glucose insulin, which are typically altered in stroke patients." (PMID 37240845, 2023). "Our results show that NaB significantly improved glucose-stimulated insulin secretion in islets from human organ donors with type 2 diabetes and in cytokine-treated INS-1 β cells." (PMID 38106138, 2023). "We recommend the use of long-acting basal insulin with longer, instead or shorter, duration, for all patients with type 2 diabetes needing treatment with basal insulin." (PMID 37233852, 2023). "To participate, clinics needed to have at least 15 patients with type 1 diabetes and at least 15 patients with type 2 diabetes on insulin." (PMID 37535407, 2023). "The current state of therapeutic inertia and delay in initiation of insulin therapy in individuals with type 2 diabetes is systemic and unsettling." (PMID 36889912, 2023). "The inability of beta cells to meet a sustained demand to produce and secrete insulin imposed by systemic insulin resistance precipitates type 2 diabetes (T2D), where de-compensation of functional beta cell mass occurs." (PMID 37233668, 2023). "Within the altered hormonal milieu among those with type 2 diabetes are changes in the insulin growth factor axis; recent studies have examined the role of insulin growth factor-1 (IGF-1) in the risk for complications from type 2 diabetes." (PMID 37438734, 2023). "We then further categorized the patients with obesity into three groups: insulin sensitive, insulin resistant, and patients diagnosed with type 2 diabetes (T2D)." (PMID 37414931, 2023). "In TS reduced sensitivity of cells to insulin is observed with higher probability of hyperinsulinemia and glucose intolerance as well as earlier development of type 2 diabetes." (PMID 37497348, 2023). "Of note, the medications for type 2 diabetes which the participants were taking at baseline in this study were either metformin, sulfonylureas, thiazolidinediones or insulin (with an exception of only 2 participants taking alpha‐glucosidase inhibitors)." (PMID 36756713, 2023).